IGF1 (insulin like growth factor 1)
Diseases named in the same sentence as IGF1 in open-access papers (continued):
Sharing a sentence is not in itself a finding about the gene and the disease.
Hypoinsulinemia (16 papers, 2002 to 2025). A decreased concentration of insulin in the blood. "RasGrf1 KO mice exhibit defects in memory consolidation, reduced body size, deficiency of IGF-1 and growth hormone, and hypoinsulinemia." (PMID 25421944, 2014). "However, skeletal muscle physiology might be at risk due to hypercorticosteronemia, hypoinsulinemia, decreased IGF-1 secretion and an oxidized redox environment associated with chronic KD consumption." (PMID 31873138, 2019). "For instance, AN is fundamentally characterized by high plasma levels of ghrelin and growth hormone (GH), together with GH resistance, normal–low insulin-like growth factor 1 (IGF-1), and hypoinsulinemia." (PMID 41010687, 2025). "Based on these findings, we concluded that hypercorticosteronemia and hypoinsulinemia, along with decreased IGF-1 secretion induced by the KD, resulted in muscle atrophy via autophagy, particularly in the Ga muscle." (PMID 31873138, 2019). "Hypoinsulinemia correlated with a decrease in IGF-1 concentration, as observed here in F1 fetuses, has been associated with growth retardation in rat fetuses." (PMID 27460165, 2016). "It has also been suggested that hepatic hypoinsulinemia may reduce insulin-like growth factor 1 (IGF-1) levels, which may contribute to IR as well by increasing growth hormone and IGF binding globulins." (PMID 39906033, 2024). "Thus, KD can lead to muscle atrophy in which hypercorticosteronemia, hypoinsulinemia, reduced insulin-like growth factor 1 (IGF-1), and oxidative stress are involved." (PMID 36145218, 2022). "In addition to hypercorticosteronemia, hypoinsulinemia and reduced IGF-1, oxidative stress might also be involved in KD-induced muscle atrophy." (PMID 31873138, 2019). "Additionally, when fetal liver growth is decreased in FGR pregnancies, a decrease in IGF1 concentrations is often observed, as well as an upregulation of the fetal liver INSR in response to fetal hypoinsulinemia." (PMID 36293384, 2022).
Nephropathy (16 papers, 2012 to 2026). A nonspecific term referring to disease or damage of the kidneys. "Overall, our findings demonstrate that intermittent exercise alleviates MI-associated kidney damage through IGF-1/IGF-1R/PI3K/AKT pathway activation and the suppression of pathological oxidative, inflammatory, and apoptotic processes." (PMID 41488924, 2025). "The IGFBP-1 gene has been suspected to be protective for nephropathy, possibly through altered IGFBP-1 binding to IGF-1 with local effect in the kidney." (PMID 22400116, 2012). "In addition, the anti-fibrotic action of SPL is thought to be due to insulin growth factor 1 (IGF-1) down-regulation, which inhibits TGF-β1 expression and hence reduces kidney damage." (PMID 36342062, 2022). "Furthermore, lots of other potential molecular mechanisms were still explored in various studies recently, including insulin-like growth factor-1 (IGF-1), connective tissue growth factor (CTGF), HIF-1α, AMPK, and Nrf2 pathways, which were found to be correlated with MetS-related nephropathy." (PMID 40697558, 2025).
prediabetes (16 papers, 2015 to 2026). "For the participants with prediabetes, we only observed the association between fish oil use and a higher serum level of IGF-1 (p < 0.001)." (PMID 37513593, 2023). "IGF-1 levels were positively correlated with both insulin and testosterone levels in women with prediabetes (r = 0.265, p = 0.008; r = 0.435, p < 0.001, respectively) but not in those without prediabetes." (PMID 41384021, 2025). "Prediabetes group had higher insulin-like growth factor-1 (IGF–1) levels and lower anti-Müllerian hormone (AMH) levels (p<0.05)." (PMID 41384021, 2025). "The mediation model indicated that elevated insulin increases serum total testosterone directly, and indirectly through increasing IGF-1 in women with prediabetes." (PMID 41384021, 2025). "A lifestyle intervention trial also found that low IGF1 levels predicted DM onset in patients with prediabetes." (PMID 38435999, 2024). "The conclusion was made that the decrease of free IGF-1 level is one of the factors of the weakening of the brain IGF-1 signaling in prediabetes, early T2DM and AD." (PMID 28031898, 2015). "In our cohort, IGF-1 levels were higher in women with prediabetes and mediated the effect of insulin on testosterone, suggesting that early dysglycemia may already activate this insulin–IGF-1–androgen axis." (PMID 41384021, 2025). "Higher bioactive IGF-1 levels might predict better metabolic outcomes following lifestyle interventions in prediabetes, potentially serving as biomarkers for personalized interventions." (PMID 38928106, 2024). "Therefore, we analyzed whether IGF-1 had mediating roles in the relationship between insulin and androgen levels in women with prediabetes." (PMID 41384021, 2025). "A study on Latino and African American vitamin D-deficient/insufficient prediabetes subjects could not detect any significant effects on serum IGF-1 after treatment with a high dose of vitamin D supplements (85,300 IU ± 16,000) for one year." (PMID 31354810, 2019). "The prediabetes group had higher FSH and IGF-1 levels than the control group (p = 0.001 and p = 0.013, respectively)." (PMID 41384021, 2025). "Insulin-like growth factor 1 (IGF- 1) and Insulin-like growth factor binding protein 1(IGFBP-1) were shown to predict T2DM onset in prediabetes." (PMID 38928106, 2024). "In accordance with these observations, patients with prediabetes and DM are demonstrated to have higher IGF-1 and GH levels than those with normal glucose tolerance (NGT); in addition, glycemic status might be predicted by IGF-1 level post-operatively." (PMID 36882643, 2023). "Although IGF-1 may not represent a primary etiological driver, its contribution to androgen biosynthesis underscores the importance of targeting insulin and IGF-1 pathways to prevent the reproductive and metabolic complications of prediabetes." (PMID 41384021, 2025).
age (15 papers, 2014 to 2025). A temporal measurement of the time period elapsed since an identifiable point in the life cycle of an organism. "The investigations into the mechanism of cGP led to the discovery of its role in regulating IGF-1 function and its association with age-related neurological conditions." (PMID 36770687, 2023). "In conclusion, our results add to the growing evidence that circulating IGF‐1 exerts complex cerebromicrovascular protective effects and that cerebromicrovascular dysfunction associated with age‐related IGF‐1 deficiency compromises multiple aspects of brain health." (PMID 28295976, 2017). "Insulin-like growth factor 1-Insulin-like growth factor 1 receptor (IGF-1-IGF-1R)signaling plays a vital role in regulating bone metabolism, and a decline in IGF-1 has been implicated in age-related bone loss." (PMID 37680888, 2023). "Insulin-like growth factor-1 (IGF-1) function declines with age and is associated with brain ageing and the progression of age-related neurological conditions." (PMID 36770687, 2023). "Increased insulin-like growth factor-1 (IGF-1) activity mitigates age-related endothelial progenitor cell dysfunction." (PMID 37900404, 2023). "This study’s findings imply that healthy elderly individuals who regularly engage in resistance exercise might delay the onset of age-related decline in executive functions, and that this protective effect may be modulated by the growth factor-IGF-1." (PMID 25713518, 2015). "Indeed, IGF-1 treatment induces muscle hypertrophy and protects against age-related atrophy." (PMID 28713486, 2017). "Here we introduce a novel invertebrate model of age-related learning deficit and how it can be ameliorated by supplementation with the polypeptides PACAP38 and IGF-1." (PMID 24846768, 2014). "However, the overall effects of suppressing IGF‐1 signaling on age‐related intervertebral disc degeneration (IDD) is not known." (PMID 33392450, 2020).
autism spectrum disorder (15 papers, 2014 to 2025). A spectrum of developmental disorders that includes autism, and Asperger syndrome. "Low levels of IGF-1 in the CSF have been associated with the development of autism-spectrum disorders, thus indicating a key physiological role of this molecule at CNS interfaces." (PMID 36890580, 2023). "In children, low IGF-1 levels are associated with reduced childhood growth, low BMI, low childhood IQ, and autism spectrum disorder." (PMID 30524358, 2018). "Neuropeptides, hormones and neuropeptide receptors participate in biological processes underlying behavior and memory, and some neuropeptides such as insulin-like growth factor 1 (IGF1) have been associated with MIA-related disorders such as autism spectrum disorders." (PMID 33834688, 2021). "Altered IGF-1 expression has been associated to autism spectrum disorders (ASD)." (PMID 25225635, 2014). "On the other hand, emerging evidence links IGF-1 with altered neurodevelopmental processes, such as autism spectrum disorder (ASD) and attention deficit hyperactive disorder (ADHD)." (PMID 40141202, 2025). "Abnormal IGF-1 signaling and decreased IGF-1 levels in the cerebrospinal fluid have also been found in autism spectrum disorder (ASD) patients." (PMID 32063830, 2020). "Research evidence accumulated in the past years in both rodent and human models for autism spectrum disorders (ASD) have established insulin-like growth factor 1 (IGF-1) as one of the most promising ASD therapeutic interventions to date." (PMID 32591005, 2020). "At present, clinical trials of IGF-1 in Autism Spectrum Disorder are ongoing, with a phase 2 trial currently recruiting (NCT01970345)." (PMID 27746717, 2016). "Abnormal insulin-like growth factor 1 (IGF-1) levels in autism spectrum disorder (ASD)." (PMID 39188438, 2024). "A link between IGF-1 pathway and autism spectrum disorders (ASD) has been proposed." (PMID 25225635, 2014).
Crohn disease (15 papers, 2008 to 2025). A gastrointestinal disorder characterized by chronic inflammation involving all layers of the intestinal wall, noncaseating granulomas affecting the intestinal wall and regional lymph nodes, and transmural fibrosis. "It was proposed that IGF‐1 supplementation could be used to promote growth in adolescents with Crohn's disease and IGF‐1 deficiency, but since high IGF‐1 levels may be carcinogenic, it was important to ensure that the dosing would only correct levels up to the normal range and not too far beyond." (PMID 27567102, 2017). "Increases in IGF1, accompanied by altered levels of SOCS3, have been associated with smooth muscle hyperplasia in the context of Crohn’s disease." (PMID 36569914, 2022). "The low bioavailability of IGFBP3 in protein losing enteropathy and Crohn’s disease partially explained the role of systemic inflammation in decreasing IGF-1 level." (PMID 29445110, 2018). "An example of this was during the design of a study to use insulin‐like growth factor (IGF‐1) in children with Crohn's disease." (PMID 27567102, 2017). "As GH acts through IGF-1 and because children with Crohn’s disease have low circulating IGF-1, rhIGF-1 is worthy of consideration, being efficacious in stimulating growth in children with conditions associated with GH insensitivity." (PMID 27965886, 2016). "In chronic inflammatory diseases such as juvenile idiopathic arthritis and Crohn's disease, elevated proinflammatory cytokines mediate growth failure through a reduction in circulating IGF-1." (PMID 24558364, 2014). "Circulating IGF-1 and IGFBP-3 are also decreased in patients with Crohn’s disease or in experimental colitis, where the inflammatory markers correlated with both proteins." (PMID 34502376, 2021). "IGFBP-5 expression is known to increase in ulcerative colitis, while IGF-1 and TGF-β1 expression is known to increase in both ulcerative colitis and Crohn's disease." (PMID 18928539, 2008). "Circulating IGFBP-3 seems to be less affected by undernutrition than IGF-1, since in Crohn’s disease patients, there is correlation between body mass index and IGF-1 but not with IGFBP-3." (PMID 34502376, 2021). "IGF-1 values declined as CRP increased, consistent with observations from a previous Zimbabwean birth cohort, and suggestive of growth hormone resistance due to chronic inflammation, as is seen in clinical disorders such as Crohn’s disease." (PMID 32059011, 2020).
delirium (15 papers, 2013 to 2025). A disorder characterized by confusion; inattentiveness; disorientation; illusions; hallucinations; agitation; and in some instances autonomic nervous system overactivity. "In patients aged 75 years and over admitted at an acute ward, a low baseline IGF-1 level was a risk factor for incident delirium." (PMID 39860413, 2025). "Consistent with previous studies, low levels of IGF‐1 and high levels of GH are independently associated with the occurrence of delirium." (PMID 37137534, 2023). "This improvement in intake brought on an increase of IGF-1, a decrease of bone loss 1 year after the fracture, lesser prevalence and intensity of delirium, and lower production of oxidative stress-derived products." (PMID 29710860, 2018). "In addition, increased serum interferon gamma (IFN-γ) and decreases in insulin-like growth factor (IGF)-1 and IL-1 have been associated with delirium in elderly patients receiving medical treatment." (PMID 38076249, 2023). "Low baseline levels of IGF-1 were associated with an increased risk of delirium incidence." (PMID 26106326, 2015). "Among the unique proteins, we focused on the top 13 most investigated proteins (IL-6, CRP, IL-8, S100B, IL-10, TNF-a, IL-1b, Cortisol, MCP-1, GFAP, IGF-1, IL-1ra, and NFL) that are significantly associated with delirium." (PMID 39700095, 2024). "Lower insulin‐like growth factor‐1 (IGF‐1, p = .024) and corticotropin‐releasing hormone (CRH, p = .005) levels were closely associated with postoperative delirium and with high levels of blood glucose (GLU, p = .023) after surgery." (PMID 37137534, 2023). "In the present study, our data also indicate that lower IGF‐1 and CRH levels are tightly associated with postoperative delirium." (PMID 37137534, 2023). "Insulin-like growth factor (IGF-1) has been reported to be involved in the pathophysiology of delirium." (PMID 32987655, 2020). "Insulin-like growth factor, IGF-1 was found as a protective factor for delirium in one study in multivariable analysis." (PMID 24610863, 2014). "Increased serum interferon gamma (IFN-γ), and decreases in the anti-inflammatory insulin-like growth factor 1 (IGF-1) and IL-1ra have been demonstrated in elderly medical patients with delirium." (PMID 25124807, 2014). "In our review, three studies reported a negative association of IGF-1 with delirium and one study reported a positive relationship." (PMID 39700095, 2024). "Due to the neuroprotective function, low levels of IGF-1 may have a significant effect on delirium severity." (PMID 26106326, 2015). "We hypothesised that delirium would be associated with increases in the pro-inflammatory cytokines IL-1β and IFN-γ, and a marker of astrocytosis GFAP, and decreases in anti-inflammatory IGF-1 and IL-1ra, and that this would be shown in the CSF." (PMID 25124807, 2014). "We have summarized the 13 most studied proteins (IL-6, CRP, IL-8, S100B, IL-10, TNF-a, IL-1b, Cortisol, MCP-1, GFAP, IGF-1, IL-1ra and NFL) about delirium." (PMID 39700095, 2024). "The study revealed that the likelihood of delirium recovery may be influenced by lower levels of IGF-1 and the lack of the APOE-e4 genotype among female patients." (PMID 39700095, 2024).
epilepsy (15 papers, 2012 to 2025). A brain disorder characterized by episodes of abnormally increased neuronal discharge resulting in transient episodes of sensory or motor neurological dysfunction, or psychic dysfunction. "Emerging research proposes peripheral blood biomarkers, including IGF-1, for epilepsy classification, providing new diagnostic approaches." (PMID 40371354, 2025). "If this is confirmed by future studies, clinical implication will be that long-term treatment with IGF-1 or its agonists may be beneficial in cases where brain injury carries relatively low risk of epilepsy, but harmful in cases where epilepsy risk is high." (PMID 27561791, 2016). "However, both brain injury and mTOR are linked to epilepsy, raising the possibility that IGF-1 may be epileptogenic." (PMID 27561791, 2016). "The reduced expression of the Alg13 gene signifies that the epilepsy-related neuropsychiatric pathology was attenuated via the regulation of GABA receptors in the IGF-1-injected APP/PS2 mice." (PMID 38473814, 2024). "Multiple studies in the disease models we reviewed found changes associated with IGF-1, mTOR, or the related AMPK pathway in AD, PD, MS and epilepsy." (PMID 36501116, 2022). "Evidence from animal studies has shown that BDNF and IGF-1 also play a partial role in the pathophysiology and epileptogenesis of epilepsy." (PMID 30524358, 2018). "Serum levels of IGF-1 were significantly correlated with the duration of epilepsy, the focus of epileptogenesis, and seizure frequency." (PMID 30524358, 2018). "Recent studies have found that BDNF and IGF-1 can modify the functions of the central nervous system (CNS) that are involved in neurological and psychiatric diseases, including epilepsy." (PMID 30524358, 2018). "In the present study, lower serum levels of IGF-1 were observed in patients with epilepsy, especially in patients with temporal lobe epilepsy." (PMID 30524358, 2018). "Correlation analysis of BDNF and IGF-1 levels with demographic variables, autonomic functions, and cerebral autoregulation parameters in patients with epilepsy and controls." (PMID 30524358, 2018). "We propose that reduced serum levels of BDNF and IGF-1 are consistent with the hypothesis that a deficit in these neurotrophic factors may contribute to the structural and functional alterations of the brain underlying the neurodegenerative process related to chronic and severe epilepsy." (PMID 30524358, 2018). "Meanwhile, patients with a longer duration of epilepsy, higher seizure frequency, and temporal lobe epilepsy had lower serum levels of IGF-1." (PMID 30524358, 2018). "Patients with a longer history of epilepsy, higher seizure frequency, and temporal lobe epilepsy had lower serum levels of IGF-1." (PMID 30524358, 2018). "Here, we considered the role of IGF-1 in development of epilepsy after brain injury, using the organotypic hippocampal culture model of post-traumatic epileptogenesis." (PMID 27561791, 2016). "At the start of IGF1 administration, S1, S2, and S3 were already under treatment for epilepsy with valproic acid at the dosage of 20 mg/kg/die." (PMID 22934177, 2012). "Both clinical trials and animal studies show that externally administered IGF-1 can reduce neural damage while improving motor and cognitive functions, underscoring its therapeutic potential for neurodegenerative disorders such as epilepsy." (PMID 40371354, 2025). "Low serum concentrations of IGF-1 have been related to more prolonged and severe cases of epilepsy." (PMID 40076950, 2025). "The reduced serum level of IGF-1 was correlated with duration of epilepsy and seizure frequency, which imply that low serum levels of IGF-1 may be related to long-term epilepsy and seizure severity." (PMID 30524358, 2018). "Correlation analysis of BDNF and IGF-1 between the seizure semiology in the patients with epilepsy." (PMID 30524358, 2018). "However, the role of BDNF and IGF-1 in epilepsy in humans has been explored only to a limited extent." (PMID 30524358, 2018).